CLDN18 (claudin 18)
Diseases named in the same sentence as CLDN18 in open-access papers (continued):
Sharing a sentence is not in itself a finding about the gene and the disease.
gastric tumor (13 papers, 2006 to 2025). "As expected, in line with another study on gastric neoplasms, CLDN18 was negatively associated with CDX2 expression in SBAs also." (PMID 35925388, 2022). "The preserved expression of CLDN18 in EBV gastric tumor cells is probably linked to key features of EBV-mediated tumorigenesis." (PMID 34834447, 2021). "Among the GCs, we found a significant association between CLDN18 expression and gastric tumour localisation (i.e. tumour localised in the gastric corpus showed a higher prevalence of CLDN18-positive cases) and Lauren Classification." (PMID 31235864, 2019). "Of note, another methodology for CLDN18 scoring, the H-score, has been proposed for gastric tumors and adopted in a few studies on PDAC." (PMID 40835751, 2025). "The CLDN18‐ARHGAP26 gene fusion was the most frequently identified among non‐hypermutated gastric tumors in the PRH cohort, occurring in 7.7% of the samples (n = 65), with three cases located in the body and two in the antrum." (PMID 40926327, 2025). "To this end, we generated the caspase-3-knockout mice and then crossed them with the Cldn18-ATK mice to elicit hyperplastic gastric tumors." (PMID 40442064, 2025). "The CLDN18 expression of primary gastric tumor, ovarian metastatic tumor and adjacent paracancerous tissues of these patients was detected via immunohistochemistry (IHC)." (PMID 38704377, 2024). "The CLDN18 gene has two splice variants encoding two isoforms: CLDN18.1, expressed in normal and lung cancer cells, and CLDN18.2, which is almost exclusively present in normal gastric mucosa cells, although it may be expressed in lung, esophageal, pancreatic, and gastric tumor cells." (PMID 38339430, 2024). "Our analysis using the TNMplot.com database showed significantly lower expression of the CLDN18 gene in gastric tumour tissues than in normal tissues." (PMID 37582713, 2023). "The pattern of CLDN18 expression may be heterogeneous, as has been observed in a proportion of gastric tumors." (PMID 40835751, 2025). "The authors reported 228 of 262 (87%) gastric tumors were CLDN18.2 positive but 135 of 262 (52%) could be eligible for IMAB362 treatment when the FAST criterion was applied." (PMID 36922936, 2022). "As we showed in this study, ZL-1211 exhibited better potency especially for CLDN18.2-low tumors than benchmark analog, suggesting that potentially up to 80% of gastric tumors may be eligible for ZL-1211 treatment." (PMID 36922936, 2022). "Interestingly, a recent study shows that claudin-18 is highly expressed in normal gastric cells and that this high expression is retained in approximately half the gastric tumors." (PMID 16836752, 2006). "However, CLDN18 has gained the most attention as a therapeutic target and has been more intensively studied in GC due to its normal expression in gastric cells combined with its consistent and stable expression in gastric tumor cells." (PMID 38339430, 2024). "CLDN18 is specifically expressed in gastric cells and may represent a marker for gastric tumors." (PMID 16836752, 2006). "According to the analysis conducted at TNMplot.com, gene expression of CLDN18 in gastric tumours was significantly lower than that in normal tissues (P < 0.01)." (PMID 37582713, 2023).
lung carcinoma (11 papers, 2011 to 2025). "Consistent with an antitumor role of claudin-18 in lung cancer, loss of claudin-18 has been reported to activate YAP, resulting in increased abundance and proliferation of known distal lung progenitors, alveolar epithelial type II (AT2) cells, and tumorigenesis in mice." (PMID 34354941, 2021). "CLDN18 (Claudin 18), a tight junction protein, has emerged as a particularly relevant biomarker in lung cancer." (PMID 40565055, 2025). "The CLDN18 is also being actively targeted in clinical trials for gastric and lung cancers, possibly due to its overexpression in tumors, offering opportunities for targeted therapy." (PMID 40565055, 2025). "Specifically for lung cancer, the highest expression level was observed in the alveolar (gene annotation: CLDN18, SFTPA1, SFTPA2, SFTPC) cell population, and erythroblasts (gene annotation not available) also increased their expression." (PMID 35631632, 2022). "In this study, we first systematically analyzed the expression of eight AT II-associated genes (AQP4, SFTPB, SFTPC, SFTPD, CLDN18, FOXA2, NKX2-1, and PGC) in lung cancer." (PMID 36203529, 2022). "In this study, we comprehensively analyzed the gene expression, prognosis value, genetic alteration, and immune cell infiltration of eight AT II-associated genes (AQP4, SFTPB, SFTPC, SFTPD, CLDN18, FOXA2, NKX2-1, and PGC) in Nonsmall Cell Lung Cancer (NSCLC)." (PMID 36203529, 2022). "The expression of CLDN18-002 (ENST00000183605.9), which encodes isoform 1, also known as isoform A1, was restricted to pulmonary normal tissues and was downregulated in lung cancer tissues." (PMID 32668412, 2020). "CLDN18 expression was downregulated in GC, lung cancer, and sarcoma (gastric stromal tumor) compared to their normal counterparts, whereas upregulation was found in esophageal, pancreatic, and prostate cancer." (PMID 32668412, 2020). "Claudin-18 inhibits Akt signaling through modulation of yes-associated protein/Taz (Yap/Taz) and insulin-like growth factor (IGF-1R) signaling in lung cancer." (PMID 31861759, 2019). "Notably, genes such as CLDN1 and CLDN18 control cell adhesion and tight junctions and were found in both gastric and lung cancer." (PMID 40565055, 2025). "Finally, CLDN18 is required for intercellular connectivity and has been reported to be involved in cell migration and metastasis, making it an oncogene in various cancer types, including pancreatic, esophageal, ovarian, and lung cancer." (PMID 36203529, 2022). "In addition to claudin 3 and 4 which may have therapeutic implications for tumor treatment in the future, claudin 18 might also be a new target for antibody mediated therapy in lung cancer." (PMID 21619599, 2011). "For lung cancer, all manuscript-referenced genes were captured by either SHAP or LIME, with notable overlaps such as MYBL2, HYAL1, CLIC5, ADGRF5, and CLDN18." (PMID 40565055, 2025). "However, many “hits” in this study with no readily apparent representation in the lung cancer methylome-related literature were found, [e.g., PR: DARS, CLDN18, APIP; GB: ARHGEF12 PRKCE], and are likely worthy of pursuit." (PMID 26683690, 2015).
lymph node metastasis (10 papers, 2020 to 2025). "Interestingly, studies have reported that CLDN18 expression is relatively preserved in lymph node metastases, suggesting that the significance of the loss of CLDN18 expression is not as high as that in PD." (PMID 38724721, 2024). "In the overall study population, claudin 18.2 positivity tended to be associated with favorable survival outcomes, possibly owing to its association with a low invasion depth and a low frequency of lymph node metastasis." (PMID 37973935, 2023). "CCA patients with CLDN18 expression more frequently had intraoperative findings of distant metastasis (P = 0.002), lymph node metastasis (P = 0.008) and positive perineural invasion (Pn1) status (P = 0.022)." (PMID 39731204, 2025). "Overall, the lymph node metastases are less frequently CLDN18.2 positive than the corresponding primary tumor, but there are also reverse cases." (PMID 40775258, 2025). "After Bonferroni correction for multiple comparisons, CLDN18.2-positive tumors still trended towards less invasive growth (pT2+, p = 0.06) and less lymph node metastasis (p = 0.07)." (PMID 40775258, 2025). "CCA patients with CLDN18 expression had a more frequently intraoperative finding of distant metastasis (P = 0.002), lymph node metastasis (P = 0.008) and positive perineural invasion (Pn1) status (P = 0.022)." (PMID 39731204, 2025). "For DFS, univariate Cox analysis showed that positive CLDN18.2 expression (HR = 1.865, 95% CI = 1.053-3.304; P = 0.033), large tumor size, serum CA19–9 elevation, advanced TNM stage, poor histological grade, MVI and lymph node metastasis were all significantly associated with disease recurrence." (PMID 40951359, 2025). "Further multivariable Cox regression identified positive CLDN18.2 expression (HR = 2.229, 95% CI = 1.125-4.415; P = 0.022), large tumor size, advanced TNM stage, poor histological grade, MVI and lymph node metastasis as independent prognostic factors for disease recurrence (all P < 0.05)." (PMID 40951359, 2025). "In 78.1% (n = 68), Claudin 18.2-negative lymph node metastasis had corresponding negative primary tumor and in 70.1% (n = 23) Claudin 18.2-positive lymph node metastasis corresponded with positive primary tumors (p < 0.0001)." (PMID 32488802, 2020). "For OS, univariate Cox analysis identified positive CLDN18.2 expression (HR = 2.545, 95% CI = 1.383-4.682; P = 0.003), serum CA19–9 elevation, advanced TNM stage, poor histological grade, microvascular invasion (MVI) and lymph node metastasis as significant factors (all P < 0.05)." (PMID 40951359, 2025). "In this case, despite the absence of standardized CLDN18.2 testing results (due to early limitations in medical conditions), the patient exhibited a significant response to LM302, with complete regression of lymph node metastases." (PMID 40900784, 2025).
asthma (9 papers, 2018 to 2025). "Claudin-18, a lung-specific claudin that is highly associated with airway epithelial barrier dysfunction in asthma, was also detected." (PMID 33868003, 2021). "Asthmatic mice with claudin-18 deficiency were found to manifest increased susceptibility to airway hypersensitivity, which indicated the contribution of claudin-18 to the pathophysiology of asthma." (PMID 36832296, 2023). "In allergic airway inflammation, as in asthma, IL-13 can reduce the expression of claudin-18, further impacting epithelial barrier function, as reflected in decreased claudin-18 in airway brushings from asthmatic patients." (PMID 41246133, 2025). "Specifically, IL-13 reduces claudin-18 production, a crucial TJ component, decreasing transepithelial electrical resistance and increasing epithelial permeability in asthma." (PMID 41303221, 2025). "A research study conducted on the tight junction proteins involved in airway epithelial cells demonstrated that the expression of claudin-18 had been reduced in patients with asthma." (PMID 36832296, 2023). "While several TJ proteins, such as ZO-1 and claudin-18, are downregulated in all asthma phenotypes (although in variable extents), claudin-4 overexpression is exclusively found in non-T2 (neutrophilic) asthma." (PMID 34248677, 2021). "Therefore, CLDN18 plays an important role in the pathogenesis of asthma and NAC diminishes airway inflammation by modulating CLDN18 expression." (PMID 34574829, 2021). "Therefore, based on the conclusions of our study, we infer that impaired claudin-18 in the terminal small airway due to extra pressure in consistent asthma attack is not conducive to asthma relief." (PMID 33868003, 2021).
gastric adenocarcinoma (8 papers, 2019 to 2026). "CLDN18 (N) is a new immunohistochemical early diagnostic marker for well‐differentiated gastric adenocarcinoma." (PMID 35861118, 2023). "While earlier reports have indicated that mice deficient in claudin-18 experienced the neoplastic transformation of gastric mucosa, more recent reports indicated the overexpression of this protein, specifically the claudin-18 splice variant 2 (claudin-18.2) in gastric adenocarcinomas." (PMID 37627123, 2023). "For 64 adenocarcinoma (40 gastric adenocarcinoma and 24 esophageal adenocarcinoma), whole-tumor sections were stained for CLDN18.2." (PMID 40775258, 2025). "From TCGA analysis, several frequently occurring alterations have been described in GS, gastric adenocarcinoma, including mutations in CDH1 and RHOA, as well as CLDN18:ARHGAP fusions." (PMID 38717153, 2024). "This suggests that claudin-18 can be a sensitive and specific marker for adenocarcinoma of the stomach and pancreatic bile duct, and claudin-18.2 is a valuable early marker of pancreatic bile duct tumors." (PMID 36959784, 2023). "Recently, nuclear staining of CLDN18 was shown to be a new immunohistochemical marker for diagnosing intramucosal well‐differentiated gastric adenocarcinoma." (PMID 35861118, 2023). "Thus, under “real world” conditions, it can be assumed that approximately one third of all esophageal and gastric adenocarcinomas are CLDN18.2-positive." (PMID 40775258, 2025). "It has been observed that 14–87% of gastric adenocarcinoma patients express CLDN18.2." (PMID 38730659, 2024). "Claudin-18 was upregulated in the diffuse form of gastric adenocarcinoma." (PMID 37627123, 2023). "We observed a significant reduction in CDH1 mutations in CCNE1-amplified gastric adenocarcinoma versus nonamplified gastric adenocarcinoma (2.9% vs. 16.4%, P = 0.0002) as well as a reduction in CLDN18:ARHGAP fusions (0% vs. 6.8%); however, the frequency of RHOA mutations were similar." (PMID 38717153, 2024).
lung adenocarcinoma (8 papers, 2013 to 2025). A carcinoma that arises from the lung and is characterized by the presence of malignant glandular epithelial cells. "Mutations in CLDN5 may cause velocardiofacial syndrome, whereas mutations in CLDN18 are related to lung adenocarcinomas." (PMID 23741331, 2013). "Knockdown of CLDN18 results in a decrease in the growth, migration, and invasion of lung adenocarcinoma cells." (PMID 40687428, 2025). "Among the top 10 genes with a high average ΔPCC in lung adenocarcinoma (LUAD), several genes such as CLDN18, ADAMTS8, PECAM1 and SFTPA1 have been known to be associated with LUAD in previous studies." (PMID 32854705, 2020). "Claudin-18 knockout mice spontaneously developed lung adenocarcinomas, and its mRNA expression was decreased in lung adenocarcinomas." (PMID 31861759, 2019). "Interestingly, Cldn18−/− mice have a high incidence of lung adenocarcinoma in old age and overexpression of Cldn18 suppresses xenograft tumor growth in vivo, suggesting a role in lung tumorigenesis." (PMID 35762622, 2022).
colorectal cancer (7 papers, 2013 to 2025). A primary or metastatic malignant neoplasm that affects the colon or rectum. "We also found that 57% of CD-associated adenocarcinoma showed CLDN18 expression and the ratio was higher than that of colitis-associated colorectal carcinomas in our previous study." (PMID 39164422, 2025). "We further analyzed the correlation between Claudin 18 protein expression in colorectal cancer tissues and clinical pathological parameters." (PMID 40936686, 2025). "Relationship between Claudin 18 protein expression in colorectal cancer tissues and clinical pathological parameters." (PMID 40936686, 2025). "Conversely, SBAs expressed CLDN18 more frequently than colorectal carcinomas (CRCs), but, of note, expression rates became similar when CRC cases were enriched, as our series was, with inflammatory bowel disease (IBD)-associated tumours." (PMID 35925388, 2022). "Additionally, this study employed immunohistochemical techniques to assess the expression levels of Claudin 18 protein in colorectal cancer tissues." (PMID 40936686, 2025). "Furthermore, we previously reported that frequent immunohistochemical CLDN18 (clone: EPR19203) expression in colitis-associated colorectal carcinomas and confirmed CLDN18-positive colorectal carcinomas only expressed CLDN 18.2 by RT-PCR." (PMID 39164422, 2025). "In the study, we used the same immunohistochemical antibody and cutoff criteria and demonstrated that CLDN18 expression was seen in 27% of colitis-associated colorectal carcinomas with an association of MUC5AC expression, while without significant association with MUC6 status." (PMID 39164422, 2025). "In colorectal cancer tissues with PNI, the positive expression rate of Claudin 18 was 56.8% (50/88), while it was 33.3% (10/30) in tissues without PNI." (PMID 40936686, 2025). "In colorectal cancer (CRC), CLDN1, CLDN2, CLDN4, and CLDN18 have been shown to either be upregulated or aberrantly expressed." (PMID 38540693, 2024). "Based on the currently available body of work on the protein expression of claudins in colorectal cancer, CLDN1, CLDN2, CLDN4, and CLDN18 have all been reported to be expressed in CRC." (PMID 38540693, 2024). "Expression of Claudin 18 protein in colorectal cancer tissues with and without perineural invasion." (PMID 40936686, 2025).
Barrett’s esophagus (5 papers, 2021 to 2025). Esophageal lesion lined with columnar metaplastic epithelium which is flat or villiform. "In the total cohort, 204 of 822 esophageal adenocarcinomas (EAC) were positive for CLDN18.2 (24.8%)." (PMID 40775258, 2025). "On the other hand, in at least one-third of esophageal adenocarcinoma cases, claudin-18 is also over-expressed." (PMID 37627123, 2023). "Claudin-18 was the dominant tight junction protein in Barrett’s esophagus in a study utilizing RT-PCR to assess the expression of 21 claudin proteins in esophageal lesions." (PMID 37627123, 2023). "Transfecting MDCK II cells with claudin-18 raised its electrical resistance and decreased, selectively, paracellular permeability to sodium and hydrogen, thus contributing to the greater acid resistance of Barrett’s esophagus." (PMID 37627123, 2023). "CLDN18.2 is the dominant claudin 18 (CLDN18) isoform expressed in both normal and malignant gastric epithelial cells and is also frequently expressed in tumors derived from organs that normally do not express CLDN18.2, including pancreatic and esophageal adenocarcinomas." (PMID 38954176, 2024).
Barrett’s oesophagus (5 papers, 2019 to 2024). "In the oesophagus, hybrid stomach-intestinal chromatin states, including those involving CLDN18, underlie human Barrett’s metaplasia." (PMID 36969060, 2023). "Our findings are in keeping with prior observations of CLDN18 expression in other gastrointestinal metaplastic and preinvasive lesions (i.e. Barrett’s oesophagus and pancreatic intraepithelial neoplasia) [31 32]." (PMID 35925388, 2022).
gastritis (5 papers, 2014 to 2025). Inflammation of the stomach. "These experiments have indicated that zolbetuximab can cause gastritis through CLDN18-targeting action." (PMID 40178693, 2025). "Stomach-specific claudin-18 (claudin-18.2) forms TJ strands in gastric epithelial cells and limits paracellular H+ efflux; its deficiency may trigger gastritis by upregulating IL-1β, TNF-α, and cyclooxygenase-2 (COX-2)/prostaglandin-E pathway." (PMID 31316506, 2019). "Additionally, these authors found that the H+ leakage into the submucosal layer of gastric tissues was higher in Cldn‐18 KO mice compared to WT mice, and was associated with the upregulation of proinflammatory cytokines which in turn induced gastritis." (PMID 24744879, 2014).
pancreatic adenocarcinoma (5 papers, 2012 to 2025). "The restricted expression makes it a potential drug target for the treatment of gastric and pancreatic adenocarcinoma, as evidenced by efforts to target CLDN18.2 via naked antibody and CAR-T modalities." (PMID 31182754, 2019). "16–23% of gastric and pancreatic adenocarcinoma samples display mid to high (H score >100) CLDN18.2 expression." (PMID 31182754, 2019).
colon cancer (4 papers, 2022 to 2024). "Patient 4, a man with colon cancer, had a CLDN18.2 expression level of 40%, 3+." (PMID 38604764, 2024).
acute respiratory distress syndrome (3 papers, 2024 to 2025). Progressive and life-threatening pulmonary distress in the absence of an underlying pulmonary condition, usually following major trauma or surgery. "IL-1β has also been reported to promote the development of acute respiratory distress syndrome (ARDS) by regulating CLDN18 through the human epidermal growth factor receptor (HER) pathway (IL-1β-HER2/HER3 axis)." (PMID 38806818, 2024).